ENSG00000283580 (novel protein)
Gene: Protein-coding gene on chromosome 1 (42,767,292 to 42,794,493, forward strand). Ensembl gene ENSG00000283580.
Genetic constraint (gnomAD): Missense variants: 178 observed, 128.28 expected, observed/expected ratio (o/e) 1.39, 90% interval 1.23 to 1.57. Synonymous variants: 70 observed, 55.36 expected, observed/expected ratio (o/e) 1.26, 90% interval 1.04 to 1.54.